GRM1 (glutamate metabotropic receptor 1)
Description:
G protein-coupled receptor for glutamate. Ligand binding causes a conformation change that triggers signaling via guanine nucleotide-binding proteins (G proteins) and modulates the activity of down-stream effectors. Signaling activates a phosphatidylinositol-calcium second messenger system. May participate in the central action of glutamate in the CNS, such as long-term potentiation in the hippocampus and long-term depression in the cerebellum. May function in the light response in the retina (By similarity). Induces GRID1 and GRID2 cation-channel activation via GNAQ-PLC-PKC pathway in dopaminergic neurons and cerebellar Purkinje cell, respectively.
Synonyms: mGluR1; GPRC1A; mGlu1; PPP1R85; SCA44; SCAR13
Tractability: Small molecule: a structure with a bound ligand is known; a high-quality ligand is known; it belongs to a druggable protein family. Antibody: UniProt places it where antibodies can reach, with high confidence; its Gene Ontology location is reachable by antibodies, with high confidence; UniProt predicts a signal peptide or a membrane-spanning region. PROTAC: ubiquitination databases record sites on it; its protein half-life has been measured; a small molecule that binds it is known.
Target class: Family C G protein-coupled receptor; Metabotropic glutamate receptor; Small molecule receptor (family C GPCR); Membrane receptor; Neurotransmitter receptor (family C GPCR)
Chemical probes: BI-1752 (high quality), BI02982816 (high quality), VU0486321 (high quality)
Gene: Protein-coding gene on chromosome 6 (146,027,646 to 146,437,601, forward strand). Ensembl gene ENSG00000152822.
Subcellular location: Cell membrane; Postsynaptic cell membrane; Cell projection, dendrite
Subcellular location (Human Protein Atlas): Vesicles
Pathways (Reactome):
Signal Transduction: Class C/3 (Metabotropic glutamate/pheromone receptors); G alpha (q) signalling events
Neuronal System: Neurexins and neuroligins
Sensory Perception: Sensory perception of sweet, bitter, and umami (glutamate) taste
Gene Ontology:
Molecular function: G protein-coupled receptor activity involved in regulation of postsynaptic membrane potential; glutamate receptor activity; protein binding; adenylate cyclase inhibiting G protein-coupled glutamate receptor activity; G protein-coupled receptor activity; G protein-coupled neurotransmitter receptor activity
Biological process: G protein-coupled receptor signaling pathway; phospholipase C-activating G protein-coupled glutamate receptor signaling pathway; phospholipase C-activating G protein-coupled receptor signaling pathway; synaptic signaling via neuropeptide; chemical synaptic transmission; G protein-coupled glutamate receptor signaling pathway; regulation of synaptic transmission, glutamatergic; adenylate cyclase-inhibiting G protein-coupled glutamate receptor signaling pathway; locomotory behavior; positive regulation of MAPK cascade; regulation of membrane potential; regulation of postsynaptic membrane potential; regulation of sensory perception of pain; sensory perception of pain; synaptic signaling
Cellular component: G protein-coupled receptor dimeric complex; G protein-coupled receptor homodimeric complex; plasma membrane; postsynaptic membrane; dendriole; postsynaptic density membrane; dendrite; glutamatergic synapse; membrane; neuron projection; nucleus; postsynaptic density; Schaffer collateral - CA1 synapse
Genetic constraint (gnomAD): Loss-of-function variants: 26 observed, 86.54 expected, observed/expected ratio (o/e) 0.3, 90% interval 0.22 to 0.42. The upper end of that interval is the gene's LOEUF score, 0.42, which puts it in group 1 of 6, group 1 being the genes least tolerant of losing a copy. Missense variants: 1,179 observed, 1,575.7 expected, observed/expected ratio (o/e) 0.75, 90% interval 0.71 to 0.79. Synonymous variants: 687 observed, 639.04 expected, observed/expected ratio (o/e) 1.08, 90% interval 1.01 to 1.14.
Homologues: Orthologues: chimpanzee GRM1 (99% identical), macaque GRM1 (99% identical), pig GRM1 (96% identical), rabbit GRM1 (96% identical), dog GRM1 (95% identical), guinea pig GRM1 (95% identical), rat Grm1 (95% identical), mouse Grm1 (94% identical), tropical clawed frog grm1 (78% identical), zebrafish grm1b (72% identical), zebrafish grm1a (67% identical), Caenorhabditis elegans mgl-2 (33% identical). Paralogues in human: GRM5 (61% identical), GRM2 (32% identical), GRM3 (32% identical), GRM4 (31% identical), GRM8 (31% identical), GRM7 (31% identical), GRM6 (29% identical).
Diseases named in the same sentence as GRM1 in open-access papers:
GRM1 is named in the same sentence as 162 diseases in open-access papers, as found by Europe PMC text mining. Sharing a sentence is not in itself a finding about the gene and the disease. The quoted sentences say what the papers report.
melanoma (84 papers, 2010 to 2025). A malignant, usually aggressive tumor composed of atypical, neoplastic melanocytes. "In a Tg(Grm1) mouse model for spontaneous melanoma, Cyld deficiency promotes cancer onset and growth." (PMID 37387450, 2023). "The gene encoding the human receptor (GRM1) is altered in melanoma by point mutations, amplification, and/or deletions." (PMID 35158973, 2022). "Experiments using cell lines generated from both primary and metastatic melanoma tissue of Tg(Grm1) Cyld−/− and Tg(Grm1) Cyld+/+ mice confirmed that loss of CYLD enhances the proliferative and migratory potential, as well as the clonogenicity in vitro." (PMID 31591386, 2019). "In this report, we demonstrate that Cyld-deficiency promotes melanoma onset and growth in the Tg(Grm1) mouse model." (PMID 31591386, 2019). "Those Grm1-Tg mice with either one or two intact SELENOK alleles developed intermediate to severe melanoma on tails and ears with the appearance of pigmented cells in the draining lymph nodes." (PMID 29568366, 2018). "The current study began when we detected Grm1 expression in a transgenic mouse model of melanoma harboring mutated BRafV600E in a PTEN null background." (PMID 29464040, 2018). "GRM1 signaling has been implicated in multiple malignant cancers including colon adenocarcinoma, melanoma, lung carcinoma, thyroid carcinoma, breast carcinoma, astrocytoma, neuroblastoma and rabdomyosarcoma." (PMID 25062106, 2014). "Somatic mutations in GRM1 has been reported in wide varieties of tumors such as melanoma, breast carcinoma, colon carcinoma, lung adenocarcinoma, brain tumors, heamatopoitic, and lymphoid tissue." (PMID 25062106, 2014). "This study found that carriers of the C allele of GRM1 rs362962 had a higher risk of developing melanoma and that the difference became greater in a subgroup of patients with a low level of sun exposure and with tumors located on the trunk and extremities." (PMID 23922822, 2013). "A single case-control study evaluated three SNPs in metabotropic glutamate receptor 1 (GRM1) for their association with risk of developing melanoma." (PMID 23922822, 2013). "GRM1 encodes a metabotropic glutamate receptor, aberrant expression of which has been suggested to play a role in the development of melanoma." (PMID 21750719, 2011). "The identification of a novel oncogene, GRM1, which plays a causative role in over 60% of melanoma cases, is especially significant in melanoma drug development." (PMID 24619402, 2010). "To finally determine whether AP2ε has an impact on melanoma development and progression in vivo, we crossbred AP2ε-deficient mice with a transgenic melanoma model (Tg(GRM1)), a murine model for spontaneous melanoma development." (PMID 38773108, 2024). "Since transcriptome sequencing did not reveal melanoma-associated mutations or single nucleotide variations in Tg(Grm1) mice, we assume, besides Grm1 overexpression, epigenetic events or changes in gene expression are important for driving melanoma development and progression in this mouse model." (PMID 29535818, 2018). "Clinical genetic analysis of GRM1 showed that single nucleotide polymorphism of the C allele of rs362962 (coding mGluR1) contributes to human melanoma susceptibility, especially in a subgroup of patients with a low level of sun exposure and tumors located on the trunk and extremities." (PMID 24610491, 2014). "The metabotropic glutamate receptor 1 (GRM1) has been implicated in melanoma development." (PMID 25593989, 2014). "Lending support to this hypothesis, the metabotropic glutamate receptor GRM1 has recently been implicated in the development of spontaneous melanoma in a mouse model, and an autocrine glutamate/GRM1 loop has been described in human melanoma." (PMID 21494657, 2011).
melanoma (continued). "26% of the expression variation of CPEB1 that regulates synaptic plasticity and is implied in cancer development and GRM1 that is involved in neurotransmitter in the central nervous system and implicated in melanoma was explained by overexpressed mir-25 and mir-15b, respectively." (PMID 21114830, 2010). "Clinical data acquired from cBioPortal for Cancer Genomics stated that in human melanomas the frequent alterations found in the GRM1 gene are results of mutations, amplifications, and/or deletions, with desmoplastic melanoma being dominated with mutations in the GRM1 gene." (PMID 34359771, 2021). "Despite the fact that the issue at hand requires more extensive studies, one may already hypothesize that different modifications of GluRs and their respective genes exist in cancer cells, as demonstrated recently by the discovery of new spliced variants of human GRM1 gene in melanoma cells." (PMID 24610491, 2014). "The Grm1 mRNA expression in lymph node tissues of wildtype and homozygous KO mice was analyzed as a marker for melanoma cell dissemination." (PMID 40182046, 2025). "Its killing of melanoma was attributed to a reduction in expression of metabotropic glutamate receptor-1 (GRM1) that enhances β-catenin signaling." (PMID 39253139, 2024). "For instance, GPCRs like metabotropic glutamate receptor 1 (GRM1) in melanoma cells and CXCR1 in hepatocytes alter the cargo of their released EVs, impacting their pro-migratory or proliferative effects." (PMID 39698417, 2024). "Stimulation of GRM1 results in the activation of two major signaling pathways critical in melanoma development/progression, MAPK and PI3K/AKT." (PMID 38732030, 2024). "TGS mice exhibit similar onset and progression of melanoma to those described for TG-3 and Tg(Grm1)EPv mice, and they mimic human melanoma development and progression." (PMID 38672652, 2024). "This also shows the first published application of CAP technology in the Tg(Grm1)EPv melanoma mouse model." (PMID 36831408, 2023). "Melanoma development and progression were studied in Cyld-epleted mice (C57BL/6 Cyld knockout) in a mouse model of spontaneous melanoma development (Tg (Grm1) Cyld +/+ mice)." (PMID 35884430, 2022). "Melanomas expressing GRM1 show elevated levels of glutamate in the tumor microenvironment, contributing to hyperactivation of the receptor and its downstream effectors." (PMID 35158973, 2022). "For an example, neuronal-specific glutamate receptor GRM1 is aberrantly expressed in melanoma and has been shown to play a critical role in melanoma development." (PMID 36137995, 2022). "A conditional transgenic model using the tetracycline-regulated system to express mGluR1 in adulthood demonstrated that Grm1 expression is required not only for the initiation of melanoma but also for its progression in vivo." (PMID 35158973, 2022). "Confirming this initial observation, transgenic mice containing Grm1 under the control of the Dct promoter (Dct::Grm1) developed melanoma with 100% penetrance." (PMID 35158973, 2022). "Tg(Grm1)EPv mice showed similar onset and progression of melanoma as the original TG-3, supporting the involvement of mGluR1 in melanoma pathogenesis." (PMID 36139432, 2022). "Co-inhibition of glutaminolysis and GRM1 have proven to be efficient in decreasing melanoma xenograft growth in vivo." (PMID 35158973, 2022). "In our model, Grm1 expression drives melanocyte hyperplasia that leads to nevi development, and progression into primary melanoma then metastatic melanoma." (PMID 34359771, 2021). "We used the transgenic tg(Grm1)EPv melanoma mouse strain that develops spontaneous, slow-growing tumors to perform immunological analysis during tumor progression." (PMID 33408092, 2021). "Loss of CYLD was shown to enhance the metastatic propensities of Grm1 driven melanoma cells by increasing their migratory, angiogenic and vascular mimicry potential." (PMID 34359771, 2021).
melanoma (continued). "The latency of onset and progression of melanoma is dependent on the number of copies of the disrupted Grm1 gene." (PMID 34359771, 2021). "In line with this, our lab has uncovered the complex role of a normal neuronal receptor, Metabotropic Glutamate Receptor 1 (protein: mGluR1, mouse gene: Grm1, human gene: GRM1) in melanoma development and progression." (PMID 34359771, 2021). "TG(Grm1)Epv develops melanoma with similar onset and progression as the original TG-3, confirming the involvement of Grm1 in melanomagenesis." (PMID 34359771, 2021). "This allowed us to quantify metastatic burden in a spontaneous syngeneic B16-F10 metastasis model, even in the absence of visible metastases, as well as in the autochthonous Tg(Grm1)/Cyld−/− melanoma model." (PMID 34830742, 2021). "In GRM1/Grm1 driven melanoma mouse models we demonstrated correlations between larger tumors with prominent vasculature." (PMID 34359771, 2021). "GRM1 mediates melanocyte transformation to melanoma through transactivation of insulin-like growth factor 1 receptors." (PMID 34360837, 2021). "We went on to show that clone B inserted into the intron 3 sequence of the Grm1 gene lead to the concurrent deletion of a 70 kb DNA sequence resulting in spontaneous melanoma development in TG-3 and its progenies." (PMID 34359771, 2021). "As the first one to discover that ectopic expression of GRM1 is the driving basis for melanoma development, our group has been actively investigating glutamatergic signaling inhibitors to treat melanoma in experimental models and patients with limited success." (PMID 32937954, 2020). "A phase II trial was conducted in patients with advanced melanoma with riluzole, an inhibitor of Grm1 signaling." (PMID 32231230, 2020). "After generating the melanoma cell lines out of tumors from Tg(Grm1) Cyld-wildtype and Tg(Grm1) Cyld-knockout mice, the cell lines were characterized using functional in vitro assays." (PMID 31591386, 2019). "GRM1 is a seven transmembrane domain comprising G-protein coupled receptor whose expression was shown to be up-regulated in human melanoma cell lines and tissues compared with melanocytes and normal tissue." (PMID 31591386, 2019). "The model was generated on the background of the Tg(Grm1) melanoma mouse model showing spontaneous melanoma development." (PMID 31591386, 2019). "First, we investigated the role of CYLD in the formation of lymphatic vessels via immunofluorescence staining on murine Tg(Grm1) Cyld+/+ and Cyld−/− melanoma tissues using LYVE-1, a specific lymphatic endothelial marker." (PMID 31591386, 2019). "Tg(Grm1) Cyld−/− mice develop melanoma significantly earlier compared to the Tg(Grm1) Cyld+/+control group." (PMID 31591386, 2019). "In the first study, it was showed that SOX10 is required for proliferation of melanoma tumor cell and that SOX10 haploinsufficiency reduces melanoma initiation in the metabotropic glutamate receptor 1 [Grm1(Tg)] transgenic mouse model." (PMID 31118886, 2019). "Herewith, we demonstrate that Cyld-deficiency leads to earlier melanoma onset and accelerated tumor growth and metastasis in the GRM1 melanoma mouse model." (PMID 31591386, 2019). "On the basis of the RNA sequencing results and to gain further insight into how CYLD acts as tumor suppressor in malignant melanoma, cell lines of both Tg(Grm1) Cyld-wildtype and Tg(Grm1) Cyld-knockout mice were generated." (PMID 31591386, 2019). "In line with the RNA sequencing data, in vitro studies with newly generated Tg(Grm1) melanoma cell lines displayed an enhanced proliferation, migration and clonogenicity in Cyld-knockout cell lines." (PMID 31591386, 2019). "Studies identified Grm1 expression in human melanoma cell lines and primary to secondary metastatic melanoma biopsies having wild-type or mutated BRaf, but not in normal melanocytes or benign nevi." (PMID 29464040, 2018).